SFXN4 (sideroflexin 4)
Description:
Mitochondrial amino-acid transporter (By similarity). Does not act as a serine transporter: not able to mediate transport of serine into mitochondria.
Synonyms: BCRM1; SLC56A4; COXPD18
Tractability: Antibody: UniProt predicts a signal peptide or a membrane-spanning region. PROTAC: ubiquitination databases record sites on it; its protein half-life has been measured.
Gene: Protein-coding gene on chromosome 10 (119,140,767 to 119,165,714, reverse strand). Ensembl gene ENSG00000183605.
Subcellular location: Mitochondrion inner membrane
Subcellular location (Human Protein Atlas): Mitochondria; Nucleoplasm; Vesicles
Pathways (Reactome):
Metabolism: Complex I biogenesis
Gene Ontology:
Molecular function: transmembrane transporter activity; monoatomic ion transmembrane transporter activity
Biological process: mitochondrial transmembrane transport; monoatomic ion transmembrane transport; monoatomic ion transport; transmembrane transport
Cellular component: mitochondrion; mitochondrial inner membrane; membrane
Genetic constraint (gnomAD): Loss-of-function variants: 29 observed, 34.71 expected, observed/expected ratio (o/e) 0.84, 90% interval 0.62 to 1.14. The upper end of that interval is the gene's LOEUF score, 1.14, which puts it in group 4 of 6, group 1 being the genes least tolerant of losing a copy. Missense variants: 283 observed, 315.87 expected, observed/expected ratio (o/e) 0.9, 90% interval 0.81 to 0.99. Synonymous variants: 106 observed, 113.1 expected, observed/expected ratio (o/e) 0.94, 90% interval 0.8 to 1.1.
Gene-disease validity (ClinGen):
ClinGen rates the evidence that SFXN4 causes each of these diseases.
mitochondrial disease (autosomal recessive): Definitive.
Homologues: Orthologues: chimpanzee SFXN4 (99% identical), macaque SFXN4 (80% identical), rabbit SFXN4 (65% identical), pig SFXN4 (61% identical), dog SFXN4 (59% identical), mouse Sfxn4 (57% identical), rat Sfxn4 (55% identical), zebrafish sfxn4 (35% identical), tropical clawed frog sfxn4 (34% identical). Paralogues in human: SFXN5 (23% identical), SFXN2 (21% identical), SFXN3 (20% identical), SFXN1 (20% identical).
Diseases named in the same sentence as SFXN4 in open-access papers:
SFXN4 is named in the same sentence as 20 diseases in open-access papers, as found by Europe PMC text mining. Sharing a sentence is not in itself a finding about the gene and the disease. The quoted sentences say what the papers report.
macrocytic anemia (5 papers, 2020 to 2024). Anemia that is characterized by increased red blood cell volume. "Mutations in SFXN4 are associated with a mitochondrial disease, characterized by macrocytic anemia and a deficiency in complex I of the mitochondrial electron transport chain." (PMID 39742262, 2024). "SFXN4 is a complex I assembly factor, and SFXN4 deficiency causes macrocytic anaemia and mitochondrial disease." (PMID 37020524, 2023). "Variants in SFXN4 induce intrauterine growth retardation, microcephaly, vision impairment, and macrocytic anemia." (PMID 33426505, 2020). "For instance, congenital megaloblastic macrocytic anemia and mitochondrial dysfunction were reported with SFXN4-related myopathy." (PMID 36140701, 2022).
Stroke (4 papers, 2023 to 2025). Sudden impairment of blood flow to a part of the brain due to occlusion or rupture of an artery to the brain. "KO models for ERAP2 and SFXN4 indicated their involvement in immune regulation and iron metabolism, respectively, both processes implicated in stroke pathogenesis." (PMID 40777745, 2025). "Emerging studies like novel ethnic-specific genetic variants, such as SUMOylation pathway in Indians, SFXN4 and TMEM108 in Africans indicate the involvement of different pathways among different ethnicities in stroke." (PMID 39268810, 2024).
hepatocellular carcinoma (3 papers, 2019 to 2024). A malignant tumor that arises from hepatocytes. "SFXN4 has been shown to be associated with multimodal immune cell infiltration in hepatocellular carcinoma." (PMID 39569192, 2024). "To test whether depletion of SFXN4 has a similar effect on mitochondrial respiration in non-erythropoietic cells, we used HepG2 (hepatocellular carcinoma) cells." (PMID 31873120, 2019).
ovarian carcinoma (3 papers, 2022 to 2024). A malignant neoplasm originating from the surface ovarian epithelium. "Further, SFXN4 expression was elevated in ovarian cancer, and knockout of SFXN4 inhibited Fe-S biogenesis, decreased DNA repair, and inhibited tumor growth in ovarian cancer." (PMID 37786439, 2023). "We used western blotting to assess levels of SFXN4 in multiple ovarian cancer cell lines and normal human ovarian surface epithelial cells (HOSE)." (PMID 36402786, 2022). "In this manuscript, we demonstrate that SFXN4, a protein that is up-regulated in ovarian cancer, plays an important role in Fe-S cluster formation in ovarian cancer cells." (PMID 36402786, 2022). "We tested the effect of SFXN4 knockdown on these models of ovarian cancer stem cells and drug resistant ovarian cancer cells." (PMID 36402786, 2022). "To explore levels of expression of SFXN4 in human ovarian cancer, we first performed immunohistochemical staining of SFXN4 in tissue obtained from ovarian cancer patients." (PMID 36402786, 2022). "Here we demonstrate that SFXN4 plays a role in synthesis of iron sulfur clusters (Fe-S) in ovarian cancer cells and ovarian cancer tumor-initiating cells, and that knockdown of SFXN4 inhibits Fe-S biogenesis in ovarian cancer cells." (PMID 36402786, 2022). "In both COV362 HGSOC cells and in FTT ovarian cancer stem cells, SFXN4 knockdown significantly increased DNA damage following cisplatin treatment, consistent with the ability of SFXN4 knockdown to attenuate DNA repair." (PMID 36402786, 2022). "Further, knockout of SFXN4 decreases DNA repair and profoundly inhibits tumor growth in a mouse model of ovarian cancer metastasis." (PMID 36402786, 2022). "A similar modest but appreciable reduction in viability was observed following knockdown of SFXN4 in COV362 ovarian cancer cells." (PMID 36402786, 2022). "Accordingly, knockdown of SFXN4 reduces proliferation and markedly and significantly reduces tumor number and mass in a mouse model of ovarian cancer peritoneal metastasis." (PMID 36402786, 2022). "Through this dual mechanism, SFXN4 inhibition heightens ovarian cancer cell sensitivity to DNA-damaging drugs and DNA repair inhibitors used in ovarian cancer therapy, such as cisplatin and PARP inhibitors." (PMID 36402786, 2022). "In this manuscript we demonstrate that the little-studied mitochondrial inner membrane protein sideroflexin 4 (SFXN4) is essential to the production of Fe-S cluster proteins in ovarian cancer cells." (PMID 36402786, 2022). "Further, we show that the decrease in Fe-S cluster formation that ensues following knockdown or knockout of SFXN4 targets two distinct but interdependent pathways that can directly or indirectly inhibit ovarian cancer cell growth." (PMID 36402786, 2022). "We next utilized a series of ovarian cancer cell lines to explore consequences of modulating levels of SFXN4." (PMID 36402786, 2022). "With the exception of OVCAR8, SFXN4 was up-regulated in all ovarian cancer cell lines examined, including cell lines representative of HGSOC (COV362, OVCAR3 and OVCAR4); endometrioid (MDAH2774 and TOV112D) and ovarian adenocarcinoma (SKOV3)." (PMID 36402786, 2022). "Previous studies have demonstrated that SFXN4 may serve as a tumor promoter in ovarian cancer by the abnormal synthesis of Fe-S clusters and the active repair of DNA sequence." (PMID 39742262, 2024). "We therefore tested whether SFXN4 knockdown would sensitize cancer stem cells and drug resistant ovarian cancer cells to drug treatment." (PMID 36402786, 2022). "SFXN4 knockdown decreased levels of all these Fe-S-containing proteins in HGSOC ovarian cancer cell lines (COV362, OVCAR3), ovarian cancer stem cells (FTT), and endometrioid cancer cells (MDAH2774), with the reduction ranging from 30 to 90%, as assessed by western blotting." (PMID 36402786, 2022). "Collectively, these results suggest that SFXN4 may represent a new target in ovarian cancer therapy." (PMID 36402786, 2022).
ovarian carcinoma (continued). "Our observation that SFXN4 knockdown decreased DNA repair suggested that SFXN4 knockdown might sensitize ovarian cancer cells to these clinically relevant chemotherapeutic drugs." (PMID 36402786, 2022). "Thus, SFXN4 knockdown impairs Fe- S cluster formation and increases mitochondrial reactive oxygen species in ovarian cancer cells." (PMID 36402786, 2022). "Cancer cells, including ovarian cancer cells, generally contain elevated levels of labile iron relative to their normal counterparts, rendering them more sensitive to oxidative stress, such as that induced by SFXN4 knockdown." (PMID 36402786, 2022). "Targeting the mitochondrial protein sideroflexin 4 (SFXN4) may provide a path to addressing this major limitation to effective ovarian cancer therapy." (PMID 36402786, 2022). "Since PARP inhibitors represent another promising chemotherapeutic in the treatment of patients with ovarian cancer, we also assessed whether SFXN4 knockdown would sensitize ovarian cancer cells to the PARP inhibitor niraparib." (PMID 36402786, 2022). "Using this assay, we first showed that Fe-S formation was significantly reduced following knockdown of SFXN4 in both HGSOC cells (COV362 and OVCAR3) and endometrioid (MDAH2774) ovarian cancer cells." (PMID 36402786, 2022). "Knockdown of SFXN4 resulted in a significant elevation of mitochondrial superoxide in both COV362 HGSOC and endometrioid MDAH2774 ovarian cancer cell lines." (PMID 36402786, 2022). "Thus, disruption of SFXN4 enhances the efficacy of platinum-based compounds and PARP inhibitors in a variety of ovarian cancer cell lines, including some with no known functional mutations in BRCA1/2 (A2780Cis, MDAH2774)." (PMID 36402786, 2022). "Accordingly, we observed that disruption of SFXN4 decreases DNA repair in vitro and in vivo and increases the efficacy of platinum-based compounds and PARP inhibitors in a variety of ovarian cancer cell lines, including some with no known functional mutations in BRCA1/2 (A2780Cis, MDAH2774." (PMID 36402786, 2022).
lung adenocarcinoma (2 papers, 2023 to 2024). A carcinoma that arises from the lung and is characterized by the presence of malignant glandular epithelial cells. "Our analysis of the GEPIA database revealed that SFXN4, another member of the SFXN family, was overexpressed in lung adenocarcinomas." (PMID 38233752, 2024).
acute myocardial infarction (1 paper, 2023). Necrosis of the myocardium, as a result of interruption of the blood supply to the area. "Based on bioinformatics analysis, it was found that SFXN4 expression was upregulated during acute myocardial infarction." (PMID 37786439, 2023).
anemia (1 paper, 2019). A reduction in the number of red blood cells, the amount of hemoglobin, and/or the volume of packed red blood cells. "Germline mutations in SFXN4 cause anemia and defects in hemoglobinization." (PMID 31873120, 2019).
endothelial dysfunction (1 paper, 2025). In vascular diseases, endothelial dysfunction is a systemic pathological state of the endothelium (the inner lining of blood vessels) and can be broadly defined as an imbalance between vasodilating and vasoconstricting substances produced by (or acting on) the endothelium. "Particularly striking was the significantly increased expression of SFXN4 in endothelial cells within MCAO-treated mice, suggesting a potential role in endothelial dysfunction and associated pathophysiological changes in IS." (PMID 40777745, 2025).
familial colorectal cancer (1 paper, 2021). Familial colon cancer is a cluster of colon cancer within a family. "Besides the description of mutations in the SFXN4 human gene causing the COXPD18 syndrome, SFXN4 was also reported to be a predisposition gene for familial colorectal cancer (CRC)." (PMID 33494450, 2021).
osteosarcoma (1 paper, 2024). A usually aggressive malignant bone-forming mesenchymal neoplasm, predominantly affecting adolescents and young adults. "The RT-qPCR, western blot and immunohistochemistry (IHC) analyses confirmed that SFXN4 displayed elevated expression at both RNA and protein levels in osteosarcoma tissues and cells, whereas SQOR exhibited heightened abundance in normal tissues and cells." (PMID 39569192, 2024). "Last but not the least, we conducted in vivo experiments to investigate the effects of SQOR and SFXN4 on the growth of osteosarcoma." (PMID 39569192, 2024). "Additionally, in vitro experiments also verified that SQOR inhibited the metastasis and invasiveness of osteosarcoma cells, while SFXN4 had the opposite effect." (PMID 39569192, 2024). "In vivo and in vitro experiments demonstrated that the expression of SQOR could suppress the growth of osteosarcoma, whereas the expression of SFXN4 promoted it." (PMID 39569192, 2024). "However, the molecular mechanism of SFXN4 in the malignant progression of osteosarcoma needs to be further investigated." (PMID 39569192, 2024). "Notably, SFXN4 was found to be highly expressed in osteosarcoma tissues and cells; it promoted the growth, migration, and invasion of osteosarcoma cells, while SQOR had the opposite effect." (PMID 39569192, 2024). "However, further research is required to determine whether SQOR and SFXN4 influence the growth of osteosarcoma through the tumor microenvironment and tumor immunity." (PMID 39569192, 2024). "Then, we performed in vivo experiments to further investigate the functions of SFXN4 and SQOR in osteosarcoma." (PMID 39569192, 2024). "According to the Kaplan-Meier (KM) survival analysis of 8 modeled genes, elevated expression levels of COL5A2, COX6A2, UQCRB, SFXN4, FAM162A and MAFF sharply shortened the survival time of osteosarcoma patients." (PMID 39569192, 2024). "Multivariate Cox regression analysis confirmed that these 8 identified genes, including 2 protective elements (SQOR and PFKFB2) and 6 hazardous factors (MAFF, COL5A2, FAM162A, UQCRB, SFXN4, and COX6A2), could independently predict the overall survival of osteosarcoma samples." (PMID 39569192, 2024).
cancer (5 papers, 2013 to 2025). A tumor composed of atypical neoplastic, often pleomorphic cells that invade other tissues. "SFXN4 expression was regulated by multiple transcription factors and miRNAs, and SFXN4 expression in HCC was associated with several cancer pathways and drug sensitivity." (PMID 37786439, 2023). "Further, disruption of SFXN4 leads to a marked reduction in cancer growth and metastases in a murine model of peritoneal ovarian cancer." (PMID 36402786, 2022). "Cancer pathway activity and drug sensitivity related to SFXN4 were explored in GSCALite." (PMID 37786439, 2023). "Our data and the literature provide indirect evidence that inhibition of SFXN4 may be tolerated by non-cancer cells, at least over the comparatively short timeframes involved in patient treatment." (PMID 36402786, 2022). "We also observed that HOSE cells express lower levels of SFXN4 than cancer cells, and it is possible that non-cancer cells may rely on alternative proteins to facilitate Fe-S cluster formation." (PMID 36402786, 2022). "Exploration of SFXN4 as a target of anti-cancer therapy may deserve consideration." (PMID 36402786, 2022). "Thus, inhibition of SFXN4 simultaneously targets two complementary pathways in cancer cells." (PMID 36402786, 2022). "Although the reason(s) underlying the differential response of cancer and non-cancer cells to inhibition of SFXN4 remain to be further explored, several mechanisms may be involved." (PMID 36402786, 2022). "UQCRBP1, positively co‐expressed with SFXN4, is also likely upregulated in HCC, suggesting a shared role in cancer progression." (PMID 40556338, 2025). "SFXN4 is regulated by various transcription factors and miRNAs, and SFXN4 might exert its role through different mechanisms, including regulating oxidative phosphorylation, reactive oxygen species and metabolic pathways, immune infiltration, and cancer pathway activity." (PMID 37786439, 2023).
mitochondrial disease (5 papers, 2019 to 2025). "For example, loss-of-function mutations in SFXN4 are associated with a rare mitochondrial disease characterized by mitochondrial complex I deficiency." (PMID 40894005, 2025). "Rare germline mutations in SFXN4 lead to phenotypic characteristics of mitochondrial disease including impaired mitochondrial respiration and hematopoetic abnormalities." (PMID 31873120, 2019).
tumor (5 papers, 2022 to 2025). "SFXN4 is upregulated in HCC and linked to poor prognosis, tumor progression, and immune infiltration." (PMID 40556338, 2025). "Nevertheless, the results of our in vivo and in vitro experiments supported a critical role of SFXN4 in tumor progression." (PMID 39569192, 2024). "The results demonstrated that SQOR exhibited a tumor-suppressive function, whereas SFXN4 facilitated tumor growth." (PMID 39569192, 2024). "Results from UALCAN database confirmed that SFXN4 expression gradually elevated along with the tumor grade proceeded (n = 407)." (PMID 37786439, 2023). "Knockout of SFXN4 led to a dramatic reduction in both tumor number and size, even when the tumor cell inoculum was increased tenfold." (PMID 36402786, 2022). "To assess the effects of SFXN4 knockout on tumor formation and growth in vivo, we injected both SFXN4 knockout and control FTT cells intraperitoneally in mice and measured tumor size and number approximately 3 weeks later." (PMID 36402786, 2022). "Knockdown of SQOR enhanced tumor growth, whereas knockdown of SFXN4 yielded an opposing effect." (PMID 39569192, 2024). "Finally, the specific molecular mechanisms by which SQOR and SFXN4 affect the tumor microenvironment and immunotherapeutic response need to be further investigated." (PMID 39569192, 2024). "In vivo, knockdown of SFXN4 inhibited the growth of tumor xenografts in mice." (PMID 37786439, 2023). "Although studies of SFXN members mainly focused on SFXN1, it is appealing that SFXN4 implicated in both tumor and non-tumor diseases." (PMID 37786439, 2023). "To verify the favorable role of SFXN4 in HCC proliferation, the mouse xenograft tumor assay were performed, by comparison of the appearance and tumor growth curves of subcutaneous tumors, we confirmed that knockdown of SFXN4 significantly hindered the growth of HCC." (PMID 37786439, 2023). "Although the remarkable efficacy of SFXN4 knockout in inhibiting tumor growth in vivo precluded assessment of the combined effects of drug treatments and SFXN4 inhibition in vivo, immunohistochemical staining of tumors revealed that nuclear RAD51 was lower in SFXN4 knockout tumors than in controls." (PMID 36402786, 2022). "Thus, targeting SFXN4 inhibits tumor growth and also exhibits the potential to reduce repair and thereby enhance the response to DNA-damaging agents in vivo." (PMID 36402786, 2022). "The ability of SFXN4 knockdown to induce oxidative stress and decrease DNA repair suggested that knockdown of SFXN4 might inhibit tumor growth." (PMID 36402786, 2022). "Furthermore, cellular experiments were performed to evaluate the impact of SFXN4 on HCC proliferation, migration and invasion, and the growth of tumor xenografts was assessed in mice." (PMID 37786439, 2023). "In TCGA database, we found the expression of SFXN4 was higher in HCC tissues than in non-paired paracancerous non-tumor tissues (3.992 ± 0.576 vs. 3.247 ± 0.284, P < 0.001), and also compared to paired paracancerous non-tumor tissues (5.283 ± 0.556 vs 4.444 ± 0.335, P < 0.001)." (PMID 37786439, 2023).
SFXN4 also shares sentences with these, for which no sentence is quoted: cerebrovascular disease (1 paper); endometrioid tumor (1); ischemic stroke (1); microcephaly (1); myopathy (1); optic nerve hypoplasia (1); ovarian adenocarcinoma (1).